KAZALD1 (Kazal type serine peptidase inhibitor domain 1)
Description:
Involved in the proliferation of osteoblasts during bone formation and bone regeneration. Promotes matrix assembly (By similarity).
Synonyms: FKSG28; FKSG40; BONO1; IGFBP-rP10
Tractability: Antibody: UniProt places it where antibodies can reach, with medium confidence; UniProt predicts a signal peptide or a membrane-spanning region; its Gene Ontology location is reachable by antibodies, with medium confidence.
Gene: Protein-coding gene on chromosome 10 (101,061,171 to 101,068,179, forward strand). Ensembl gene ENSG00000107821.
Subcellular location: Secreted, extracellular space, extracellular matrix
Gene Ontology:
Molecular function: protein binding; receptor ligand activity; insulin-like growth factor binding
Biological process: regulation of signal transduction; regulation of cell growth; signal transduction
Cellular component: interstitial matrix; extracellular matrix; extracellular region
Genetic constraint (gnomAD): Loss-of-function variants: 32 observed, 26.83 expected, observed/expected ratio (o/e) 1.19, 90% interval 0.9 to 1.6. The upper end of that interval is the gene's LOEUF score, 1.6, which puts it in group 6 of 6, group 1 being the genes least tolerant of losing a copy. Missense variants: 444 observed, 371.13 expected, observed/expected ratio (o/e) 1.2, 90% interval 1.11 to 1.29. Synonymous variants: 179 observed, 159.24 expected, observed/expected ratio (o/e) 1.12, 90% interval 0.99 to 1.27.
Homologues: Orthologues: chimpanzee KAZALD1 (98% identical), macaque KAZALD1 (95% identical), dog KAZALD1 (91% identical), pig KAZALD1 (90% identical), rabbit KAZALD1 (85% identical), mouse Kazald1 (84% identical), rat Kazald1 (83% identical), guinea pig KAZALD1 (81% identical), tropical clawed frog kazald1 (63% identical), zebrafish kazald3 (41% identical). Paralogues in human: IGFBPL1 (32% identical), IGFBP7 (31% identical).
Diseases named in the same sentence as KAZALD1 in open-access papers:
KAZALD1 is named in the same sentence as 19 diseases in open-access papers, as found by Europe PMC text mining. Sharing a sentence is not in itself a finding about the gene and the disease. The quoted sentences say what the papers report.
colon cancers (2 papers, 2014 to 2025). "Recent studies have further indicated that IGFBP7 expression is repressed by methylation –dependent mechanisms in colon cancers while its paralog KAZALD1 is often methylated and silenced in MPM." (PMID 24690739, 2014). "KAZALD1 is involved in colon tumor development and plays a role in wool fitness in sheep." (PMID 40811742, 2025).
glioma (2 papers, 2015 to 2025). A benign or malignant brain and spinal cord tumor that arises from glial cells (astrocytes, oligodendrocytes, ependymal cells). "Kazald1, a secreted member of the IGFBP superfamily, has been associated in limited studies with glioma progression, limb regeneration, and osteoblast proliferation." (PMID 41041066, 2025). "In tumorigenesis, Kazald1 methylation level is highly correlated with glioma progression." (PMID 41041066, 2025). "In the methylation data the candidate of interest Kazal-type serine peptidase inhibitor domain 1 (Kazald1) has been shown to demonstrate a shorter overall survival for patients with hypomethylation in gliomas and is suggested to promote progression through invasion and proliferation." (PMID 26315110, 2015).
adenoma (1 paper, 2025). A neoplasm arising from the epithelium. "In our study, LS adenomas with low- and high-grade dysplasia also displayed hypomethylated KAZALD1 DMPs in promoter area (n = 2 and 4, respectively)." (PMID 40753397, 2025).
demyelinating disease (1 paper, 2018). A broad group of disorders that affect the myelin sheaths that cover the neurons. "More specifically, RTN4 is related to Demyelinating Disease and KAZALD1 is related to Lobar Holoprosencephaly." (PMID 29671403, 2018).
fibrosis (1 paper, 2025). the formation of excess fibrous connective tissue in an organ or tissue in a reparative or reactive process. "During cartilage fibrosis, Kazald1 expression was significantly down-regulated and becomes imbalanced with TGF-β1." (PMID 41041066, 2025).
gastric cancer (1 paper, 2022). A primary or metastatic malignant neoplasm involving the stomach. "The gene product of KAZALD1 is identified as a serum biomarker in gastric cancer, and is found hypermethylated in malignant pleural mesothelioma, while low levels of DNA methylation are found associated with longer survival." (PMID 35163690, 2022).
glioblastoma (1 paper, 2025). The most malignant astrocytic tumor (WHO grade IV). "Research indicates that the hypomethylation of the KAZALD1 promoter serves as a crucial prognostic marker for glioblastoma." (PMID 41497483, 2025).
melanoma (1 paper, 2023). A malignant, usually aggressive tumor composed of atypical, neoplastic melanocytes. "Associations with the presence of TERT promoter mutations revealed an overlap of 30 genes in the three bulk RNA-seq cohorts (in melanoma and across entities), of which six genes were consistently up- or down-regulated (up: ARL17A, FBF1, KAZALD1, PRAF2; down: PLEKHB2, RASGRP3)." (PMID 37418389, 2023).
osteoblastic osteosarcoma (1 paper, 2024). A conventional osteosarcoma characterized by the predominance of osteoid matrix. "KAZALD1 is overexpressed in osteoblastic osteosarcoma and carcinoma-associated fibroblasts and CILP under expression is a known feature of the disease." (PMID 39701601, 2024).
osteosarcoma (1 paper, 2024). A usually aggressive malignant bone-forming mesenchymal neoplasm, predominantly affecting adolescents and young adults. "Similarly, several survival-related genes, including MUC1, COL13A1, KAZALD1, and JAG2, were identified as prognostic markers in osteosarcoma by scRNA-seq and TARGET analysis." (PMID 39324133, 2024).
pleural mesothelioma (1 paper, 2020). A neoplasm that arises from the mesothelial cells of the pleura. "KAZALD1, which is a DNA hyper-methylated gene, was particularly methylated in pleural mesothelioma and may act as prospective diagnostic markers." (PMID 32679676, 2020).
renal fibrosis (1 paper, 2025). A final common manifestation of a wide variety of chronic kidney diseases characterized by glomerulosclerosis and tubulointerstitial fibrosis. "Its mechanisms may involve promoting renal fibrosis through oxidative stress and inflammatory pathways and further aggravating DN progression by influencing PM‐RGs such as KAZALD1, GLCE, and RPRD1B." (PMID 41497483, 2025).
KAZALD1 also shares sentences with these, for which no sentence is quoted: tumor (3 papers); breast carcinoma (1); carcinoma (1); Hypermetropia (1); lobar holoprosencephaly (1); malignant pleural mesothelioma (1); myopia (1).